UBE2C (ubiquitin conjugating enzyme E2 C)
Diseases named in the same sentence as UBE2C in open-access papers (continued):
Sharing a sentence is not in itself a finding about the gene and the disease.
renal carcinoma (2 papers, 2019 to 2022). A carcinoma arising from the epithelium of the renal parenchyma or the renal pelvis. "We used the siRNA technique to downregulate CDC20 and UBE2C in two renal cancer cell lines to investigate their role in renal carcinoma." (PMID 36385010, 2022). "Knockdown of UBE2C significantly inhibited proliferation and migration in renal cancer 786-O cells in vitro, confirming our bioinformatics analyses." (PMID 36385010, 2022). "In normal renal tissues only modest levels of UBE2C protein expression were observed, but in renal cancer tissues medium and high levels of UBE2C expression were detected." (PMID 36385010, 2022). "Particularly, the expression of UBE2C may be crucial for the prognosis and immunological treatment of renal cancer." (PMID 36385010, 2022). "Taken together, these studies support the notion that UBE2C and CDC20 are hub genes in different types of renal cancer." (PMID 36385010, 2022). "However, modest levels of CDC20 protein expression were found in both normal and renal cancer tissues, indicating that the transcriptional and translational levels of UBE2C expression in PRCC were not differential." (PMID 36385010, 2022).
retinoblastoma (2 papers, 2021 to 2025). A malignant tumor that originates in the nuclear layer of the retina. "As expected, we found that UBE2C was highly expressed in the retinoblastoma cells compared with that in the normal control ARPE-19 cells." (PMID 34815392, 2021). "The results clearly showed that UBE2C protein expression was remarkably increased in the tissues of retinoblastoma corrected from the younger patients and especially the metastasis patients compared with that of children over 3 years old." (PMID 34815392, 2021). "In this report, we clearly demonstrated that UBE2C was strongly correlated with the degree of malignancy and metastasis of retinoblastoma." (PMID 34815392, 2021). "The results clearly showed that UBE2C was remarkably increased in state-5, especially in retinoblastoma cells-c5." (PMID 34815392, 2021). "The cells enriched in state-5 at the terminal of the branch shared a highly similar global expression profile with retinoblastoma cells that possess cell cycle (UBE2C, PTTG1, CCNB1) and proliferation (MKI67) properties." (PMID 34815392, 2021). "To explore the prognostic role of UBE2C in retinoblastoma, we then examined the expression of UBE2C in bulk tumours." (PMID 34815392, 2021). "To provide evidence for the specificity of UBE2C in retinoblastoma, we then examined the expression of UBE2C in retinoblastoma cell lines." (PMID 34815392, 2021). "We next explored the prognostic significance of UBE2C in retinoblastoma." (PMID 34815392, 2021). "Taken together, UBE2C played a regulatory role in retinoblastoma progression in vitro and in vivo, and could be regarded as a potential therapeutic target." (PMID 34815392, 2021). "Although we cannot eliminate other genes promoted tumorigenesis during critical stages in retinoblastoma development, this is the first study to imply that UBE2C as the crucial transcription regulatory factor during the malignant tumour cells differentiation reprogramming." (PMID 34815392, 2021). "As expected, we noted that cone precursors were the root cells that were required for initiating the delamination and migration process of retinoblastoma development, while determination of the fate of retinoblastoma cells was accompanied by increased UBE2C expression." (PMID 34815392, 2021). "Thus, UBE2C acts as the critical gene that might coordinately regulate the occurrence of intratumoural heterogeneity and further tumour progression in retinoblastoma." (PMID 34815392, 2021). "Here, for the first time, we captured molecular profiles for human retinoblastoma, indicating the cone precursors and retinoblastoma cells differentiation state in which the highly expressed UBE2C gene might serve as an indicator for evaluating the mature and malignancy of retinoblastoma." (PMID 34815392, 2021). "However, few studies explored the role of the UBE2C in retinoblastoma." (PMID 34815392, 2021). "In addition, UBE2C represented as a “pivot” gene in retinoblastoma cells branch." (PMID 34815392, 2021). "Interestingly, the level of expression of UBE2C, EBF3, GAP43, and PDC was reminiscent of a profile of non-proliferative subtype 1 retinoblastoma (cluster 1 population), also cited in previous studies as cone precursors and cone precursor-like." (PMID 40898088, 2025).
serous ovarian adenocarcinoma (2 papers, 2021 to 2022). "By analysis of the clinical data, we found that CDCA3 and UBE2C were associated with poor prognosis in serous ovarian cancer patients." (PMID 34577856, 2021). "We suggested that CDCA3 and UBE2C may represent valuable biomarkers to predict the outcome of serous ovarian cancer." (PMID 34577856, 2021). "This showed that higher expressions of CDCA3, CENPF, NCAPG, RRM2, UBE2C, and NBEA were associated with worse OS regardless of serous ovarian cancer stages." (PMID 34577856, 2021).
Skin cutaneous melanoma (2 papers, 2022 to 2024). "Upregulated UBE2C expression was significantly correlated with poor prognosis and Overall survival (OS) of patients with ACC, BRCA, KIRC, KIRP, Low grade glioma (LGG), LUAD, MESO, PAAD, and Skin cutaneous melanoma (SKCM)." (PMID 38577722, 2024).
acute leukemia (1 paper, 2024). A clonal (malignant) hematopoietic disorder with an acute onset, affecting the bone marrow and the peripheral blood. "The data from GEPIA analysis indicated that UBE2C was highly expressed in acute leukemia samples (P < 0.01)." (PMID 38637730, 2024).
benign prostate hyperplasia (1 paper, 2022). "Secondly, we did not include the benign prostate hyperplasia (BPH) tissue as UBE2C was also reported to be expressed in it and to be a critical factor in pathogenesis." (PMID 36430352, 2022).
brain cancer (1 paper, 2023). A primary or metastatic malignant neoplasm affecting the brain. "Both strategies can be applied to identify and validate novel UBE2C inhibitors for the treatment of brain cancer patients." (PMID 37958776, 2023). "Emerging evidence has suggested that the ubiquitin-conjugating enzyme E2C (UBE2C), essential for controlling cell cycle progression, is overexpressed in diverse malignancies, including brain cancer." (PMID 37958776, 2023). "Thus, there is a need to further explore the role of UBE2C in malignant brain cancer and to develop effective targeted therapies for patients with this deadly disease." (PMID 37958776, 2023).
calcific aortic valve disease (1 paper, 2021). "Aberrant expression of UBE2C leads to the degradation of pVHL (von Hippel-Lindau tumor suppressor), which increases HIF-1α levels, resulting in endothelial inflammation and epithelial-mesenchymal transition in calcific aortic valve disease." (PMID 34257576, 2021).
cardiomyopathy (1 paper, 2020). A disease of the heart muscle or myocardium proper. "We assumed that miR-1246 might target UBE2C, TNNT1, TRAIP, and UCHL1 during the regulation of ubiquitin-mediated proteolysis, glycosaminoglycan binding, DNA metabolism, the PI3K–Akt–mTOR signaling pathway, the neurotrophin and cardiomyopathy signaling pathway, and the MAPK signaling pathway." (PMID 33050659, 2020).
cervical tumor (1 paper, 2020). "The H-scores of the TMA samples showed that 89.4% (263/294) of the tumor tissue (T) samples were UBE2C positive, and expression of UBE2C was significantly higher in cervical tumor (T) tissues than in non-tumor (N) tissues." (PMID 33396624, 2020).
colitis (1 paper, 2018). Inflammation of the colon. "A 16-gene signature (CARD12, CCL3, CCR3, CXCL1, F5, FAM210B, GADD45A, IL18bp, IL2RA, IL5, IL8, MMP9, PTGS2, SOCS3, TLR9 and UBE2C) was identified from 30 days post-tremelimumab initiation blood that discriminated patients developing grade 0–1 from grade 2–4 diarrhea/colitis." (PMID 30227886, 2018).
colorectal adenocarcinoma (1 paper, 2024). The most common type of colorectal carcinoma. "UBE2C has the highest mutation frequency in patients with colorectal adenocarcinoma (~8%)." (PMID 38577722, 2024).
complement component 7 deficiency (1 paper, 2025). "UBE2C (ubiquitin-conjugating enzyme E2C) encodes a protein that is associated with diseases such as methotrexate-associated lymphoid hyperplasia and complement component 7 deficiency." (PMID 40324248, 2025).
Ewing sarcoma (1 paper, 2021). A small round cell tumor that lacks morphologic, immunohistochemical, and electron microscopic evidence of neuroectodermal differentiation. "Moreover, we checked the expression of several genes that were previously reported to be affected by YK-4-279 in Ewing’s sarcoma and found that the expressions of TERT and UBE2C (Ubiquitin Conjugating Enzyme E2-C) were reduced after YK-4-279 treatment in our cell lines." (PMID 34221969, 2021).
Hematuria (1 paper, 2016). The presence of blood in the urine. "The levels of urinary UBE2C cell-free RNA were significantly higher in BC samples than in normal and hematuria control samples." (PMID 27528424, 2016). "In conclusion, the levels of urinary UBE2C cell-free RNA were significantly higher in samples from BC patients than in samples from normal healthy individuals or from patients with hematuria." (PMID 27528424, 2016).
intestinal-type carcinoma (1 paper, 2018). "We explored the biological function of UBE2C gene in vitro, and found that the overexpression of UBE2C is related to gain of DNA copy number caused by CIN of intestinal-type carcinoma." (PMID 30116193, 2018).
iron-deficiency (1 paper, 2011). "Proteins are tagged for degradation by ubiquitin and the process catalysed by ubiquitin-conjugating enzymes such as Ube2c, which was shown to be down-regulated by both protein and iron-deficiency in RHLs in our microarray and by real-time PCR." (PMID 21858025, 2011).
leiomyosarcoma (1 paper, 2020). An uncommon, aggressive malignant smooth muscle neoplasm, usually occurring in post-menopausal women. "In human leiomyosarcomas (LMS), expression of UBE2C was found in 12 of 26 (46%), of CENPE in 7 of 26 (27%), of HAS2 in 7 of 26 (25%) and of CREB3L2 in 20 of 27 (74%) human leiomyosarcoma cores." (PMID 32898143, 2020).
metastatic melanoma (1 paper, 2023). A melanoma that has spread from its primary site to another anatomic site. "Among the top 5 candidate genes (UBE2C, ASF1B, FOXM1, HJURP, and KIF18B), UBE2C was the most frequently associated with poor prognosis in publicly available clinical datasets from diverse cancer types, including metastatic melanoma." (PMID 37215954, 2023).
microhematuria (1 paper, 2022). "UBE2C mRNA was found to be particularly useful in discriminating the origin of hematuria, QGAP3 in differential diagnosis in gross and microhematuria, whilst N-Myc mRNA levels were highly correlated with grade and stage of the disease." (PMID 35955004, 2022).
mucinous adenocarcinoma (1 paper, 2019). An invasive adenocarcinoma composed of malignant glandular cells which contain intracytoplasmic mucin. "In relation to digestive system tumors, COAD tumors showed increased UBE2C levels in adenocarcinoma and mucinous-adenocarcinoma." (PMID 31067633, 2019).
serous endometrial adenocarcinoma (1 paper, 2020). "In TCGA cohort, overexpressed expression of UBE2C in EC was associated with advanced clinical pathologic characteristics (poor differentiation, serous endometrial adenocarcinoma, FIGO stage II~IV, distant metastasis), and poor prognosis." (PMID 31942195, 2020).
tongue cancer (1 paper, 2020). A malignant neoplasm affecting the tongue. "However, reduced expression levels of ADLH/A1 and ABCG2 stemness markers were only found in UBE2C-knockdown Ca9-22 cells but not in UBE2C-knockdown SAS cells, which indicating that UBE2C might play a more important role in cancer stemness in tongue carcinoma." (PMID 32899896, 2020).
viral hepatitis (1 paper, 2020). An acute or chronic inflammation of the liver parenchyma caused by viruses. "DNA hypomethylation of DCAF4L2, CKLF and UBE2C was observed in both NASH-related and viral hepatitis-related HCCs, whereas that of TRIM4, PRC1 and TUBA1B occurred in a NASH-related HCC-specific manner." (PMID 32685988, 2020).
cancer (202 papers, 2005 to 2026). A tumor composed of atypical neoplastic, often pleomorphic cells that invade other tissues. "Overexpression of UBE2C has been implicated in several cancers, where its dysregulation promotes tumorigenesis by enhancing cell proliferation and inhibiting apoptosis." (PMID 41492994, 2026). "Here, we investigated the gene expression profiles of UBE2C in both healthy individuals and cancer patients to evaluate its diagnostic value." (PMID 38577722, 2024). "As previously reported, UBE2C was highly expressed in various human cancers and associated with adverse outcomes, which is consistent with our acquired results." (PMID 39479352, 2024). "The gene UBE2C encodes a protein called ubiquitin-conjugating enzyme E2 C, which has been found to regulate cell proliferation and cancer cell invasion." (PMID 38637730, 2024). "Overall, our study and previous research highlight the significance of UBE2C as a diagnostic tool for early detection and a potential therapeutic target in various cancers." (PMID 38577722, 2024). "Previous studies have reported the high expression of UBE2C in several cancers, and the overexpression of UBE2C is associated with cell proliferation, metastasis and poor prognosis of different tumours." (PMID 37848988, 2023). "We identified UBE2C as a differentially expressed gene in human BM and showed that high levels of UBE2C are associated with shorter survival in cancer patients with brain metastatic disease." (PMID 37215954, 2023). "UBE2C, encoding an E2 ubiquitin ligase often overexpressed in cancer cells, was markedly upregulated in 5 of the 6 HB cell lines." (PMID 37377594, 2023). "These cancer-tissue association and in vitro cell-based studies suggested that UBE2C is a Kras-cooperative gene." (PMID 36548081, 2023). "The survival analyses revealed that the high expression of UBE2C was significantly associated with a poor prognosis in patients of 10 cancer types while PLK1 was also associated with 11 cancer types." (PMID 37958642, 2023). "While previous in vitro studies showed that UBE2C plays a growth-promoting role in cancer cell lines, the underlying mechanism remains elusive." (PMID 36548081, 2023). "It was interesting to note that a change in the molar ratio of the drug combination from 0.8 to 1.5 causes overexpression of a potential cancer biomarker such as UBE2C." (PMID 35214193, 2022). "Our pan-cancer analysis of UBE2C was the first to identify that the expression of UBE2C was consistently higher in almost all cancer types and that it was associated with cancer stage, clinical prognosis, and DNA methylation." (PMID 35804892, 2022). "It followed that UBE2C high expression caused a poor clinical outcome of patients in the majority of cancer types including THCA." (PMID 35332135, 2022). "Through pan-cancer analysis, we found that UBE2C was highly overexpressed in almost all cancer types, and UBE2C high expression caused a poor clinical outcome in the majority of cancers." (PMID 35332135, 2022). "We examined the relationship between gene expression of CDC20 and UBE2C and 24 immunoinhibitors among pan cancer to evaluate their clinical significance in association with immune moderation." (PMID 36385010, 2022). "UBE2T and UBE2C have been previously associated with cancer progression and poor outcome in several solid tumors, although genomic evidence in BC is recent and limited." (PMID 33671201, 2021). "The results suggested that UBE2C expression was positively associated with the immune checkpoint-related genes in 31 cancers, which mainly included CD274, CTLA4, HAVCR2, LAG3, PDCD1, PDCD1LG2, SIGLEC15, and TIGIT." (PMID 34858987, 2021). "In this study, we found that UBE2C expression was positively associated with an immune checkpoint-related gene in 31 cancer types." (PMID 34858987, 2021). "A number of studies showed highexpression of UBE2C is associated with aggressive progression and poor outcomes of various types of cancer." (PMID 35540695, 2021).